ITPA (inosine triphosphatase)
Diseases named in the same sentence as ITPA in open-access papers (continued):
Sharing a sentence is not in itself a finding about the gene and the disease.
chronic hepatitis C (7 papers, 2012 to 2025). "It has also been reported that inosine triphosphatase (ITPA) gene variants protect against ribavirin-induced hemolytic anemia in chronic hepatitis C patients." (PMID 23012624, 2012). "Here, we report a case of severe thrombocytopenia that developed in a patient with chronic hepatitis C treated with PEG-IFN-α2a plus ribavirin in spite of having the ITPA-CC genotype." (PMID 24621321, 2014). "We report a case of severe thrombocytopenia that developed in a patient with chronic hepatitis C treated with pegylated interferon combined with ribavirin in spite of having the inosine triphosphatase-CC genotype." (PMID 24621321, 2014). "Therefore, this case of severe thrombocytopenia that developed in a patient with chronic hepatitis C treated with PEG-IFN/RBV in spite of the patient having the ITPA-CC genotype should be kept in mind." (PMID 24621321, 2014).
hepatitis C (7 papers, 2012 to 2024). "Given the widespread use of thiopurines, and magnitude of individuals infected with hepatitis C, while considering that roughly one third of the world population has ITPA polymorphism, it seems plausible that development of these therapies will be met with considerable need." (PMID 27770805, 2016). "Decreased ITPase activity and the frequent ITPA SNPs are associated with a reduced risk to develop ribavirin-induced haemolytic anaemia in patients on treatment for hepatitis C, and with an increased risk of AEs in patients treated with thiopurines." (PMID 29329318, 2018). "ITPA variation has also been associated with reduced relapse risk and achieving sustained virological response (SVR) for hepatitis C patients." (PMID 27770805, 2016). "Multiple reports have demonstrated that ITPA status affects outcomes of hepatitis C treatment and thiopurine therapy." (PMID 27770805, 2016). "Based on these findings, it has been suggested that status of the ITPA locus, or ITPase activity, should be considered for patients beginning hepatitis C therapies which include ribavirin." (PMID 27770805, 2016). "It is also worth mentioning that, in some cases, the defect of ITPA could be a benefit in special situations, because the condition prevents hemolytic anemia in hepatitis C patients treated by ribavirin." (PMID 22384212, 2012).
leukopenia (7 papers, 2015 to 2023). "As reported in an Egyptian ALL study, ITPA rs7270101 was associated with the risk of neutropenia and leukopenia." (PMID 37251339, 2023). "Recent studies have shown that ITPA polymorphisms are significantly associated with flu-like symptoms, rash, pancreatitis and leukopenia." (PMID 26360046, 2015). "However, the study indicated that leukopenia cannot be clearly attributed to the ITPA (94C>A) mutation as there may be other influencing factors." (PMID 34084143, 2021). "Among 77 patients with wild-type (CC) ITPA 94C>A, the number of patients exhibiting leukopenia, thrombocytopenia, and neutropenia was seven (9.1%), 24 (31.2%) and three (8.6%), respectively." (PMID 33846471, 2021). "The results were consistent with these of a recent study in Thai patients with ALL, which also demonstrated a non-association between ITPA variants and 6-MP induced leukopenia and cumulative 6-MP doses at any time point during maintenance." (PMID 29720126, 2018). "Furthermore, in an exploratory analysis, genetic variants in TPMT, ITPA, and NUDT15 were compared and screened to determine the optimal risk prediction of 6-MP-induced leukopenia." (PMID 29720126, 2018). "In the leukopenia group, the percentages of woman and the rate of ITPA 94C>A mutation were higher than those in the without-leukopenia group (P < 0.05)." (PMID 26360046, 2015). "Seven out of 19 patients (36.8%) with the ITPA 94C>A mutation developed leukopenia; however, this mutation may not unequivocally increase the risk of developing adverse reactions to thiopurines." (PMID 26360046, 2015). "Seven out of 19 patients (36.8%) with the ITPA 94C>A mutation developed leukopenia; however, this mutation may not unequivocally increase the risk of developing leukopenia." (PMID 26360046, 2015). "Therefore, compared with TPMT*3C and ITPA 94C>A, the detection of NUDT15 c.415C>T in the Chinese population may have better predictive value for AZA-induced myelosuppression with leukopenia and neutropenia as the primary manifestations." (PMID 33846471, 2021).
neutropenia (6 papers, 2012 to 2023). A decrease in the number of neutrophils found in the blood. "On the other hand, patients with the ITPA rs7270101 AC genotype had about two-fold (p = 0.035) increased risk of developing early-onset grade 4 neutropenia." (PMID 37251339, 2023). "Of note, the association between ITPA 94 C > A and neutropenia in children with ALL was verified in recent systematic reviews and meta-analysis." (PMID 36238550, 2022). "Specifically, pediatric ALL patients with an ITPA 94 C > A variant had an approximately 2.5 times higher risk of suffering from neutropenia." (PMID 36238550, 2022). "Despite the inconsistencies in individual results, we found that ITPA 94C>A polymorphism may be associated with an increased risk of 6-MP-induced neutropenia and hepatotoxicity." (PMID 35455413, 2022). "In previous studies, ITPA genotype significantly influenced the risk of fever and neutropenia, but this did not influence survival rates." (PMID 23029095, 2012).
Thrombocytopenia (6 papers, 2012 to 2021). A reduction in the number of circulating thrombocytes. "It is a worthwhile case because, in spite of having the ITPA-CC genotype, the patient developed severe thrombocytopenia caused by the PEG-IFN/RBV treatment." (PMID 24621321, 2014). "In thrombocytopenia caused by PEG-IFN/RBV, there is a tendency that patients with the ITPA-CC genotype are considered to be less at risk than those with the ITPA-CA/AA genotype." (PMID 24621321, 2014). "Recently, genome-wide association studies have identified that the genetic variant of rs1127354 single nucleotide polymorphisms (SNPs) in the inosine triphosphatase (ITPA) gene, which encodes a protein that hydrolyses inosine triphosphate (ITP), has been found to be associated with thrombocytopenia." (PMID 24621321, 2014). "We should pay careful attention in the differential diagnosis for patients with the inosine triphosphatase-CC genotype because, although rare, severe thrombocytopenia could occur." (PMID 24621321, 2014). "Progression of thrombocytopenia in patients carrying each ITPA genotype was compared in each group." (PMID 23145809, 2012). "Splenectomy improved SVR rate, especially among patients carrying the IL28B minor genotype, protecting against hemolytic anemia or thrombocytopenia, regardless of ITPA genetic variants." (PMID 23145809, 2012). "However, we should pay careful attention in the differential diagnosis for patients with the ITPA-CC genotype because, although rare, severe thrombocytopenia could occur." (PMID 24621321, 2014).
Cirrhosis (5 papers, 2012 to 2023). A chronic disorder of the liver in which liver tissue becomes scarred and is partially replaced by regenerative nodules and fibrotic tissue resulting in loss of liver function. "In the present study we aimed to explore the role of IL28B, APOH and ITPA SNPs on the outcomes of triple therapy including telaprevir or boceprevir in patients with compensated cirrhosis chronically infected with HCV-1." (PMID 26670100, 2015). "We explored the role of IL28B, APOH and ITPA SNPs on the outcomes of triple therapy including telaprevir or boceprevir in patients with compensated cirrhosis chronically infected with HCV-1." (PMID 26670100, 2015). "Thirty-seven patients with HCV-induced cirrhosis who underwent laparoscopic splenectomy (Spx group) and 90 who did not (non-Spx group) were genotyped for IL28B and ITPA." (PMID 23145809, 2012).
Encephalopathy (5 papers, 2016 to 2022). Encephalopathy is a term that means brain disease, damage, or malfunction. "ITPA mutation is also associated with young-onset tuberculosis susceptibility and is responsible for early infantile encephalopathy." (PMID 35159194, 2022). "In humans, it was recently reported that patients with homozygous loss-of-function mutations in the ITPA gene showed severe encephalopathy with epileptic seizure and microcephaly or dilated cardiomyopathy." (PMID 33208550, 2020). "At present, encephalopathy due to ITPA deficiency is described as “early infantile epileptic encephalopathy 35 (EIEE35)” in the Online Mendelian Inheritance in Man (OMIM) database (OMIM #616647)." (PMID 33208550, 2020). "In humans, ITPA deficiency causes severe encephalopathy with epileptic seizure, microcephaly, and developmental retardation." (PMID 33208550, 2020). "More recently, a whole exome sequencing project revealed that very rare, severe human ITPA mutation results in early infantile encephalopathy and death." (PMID 27770805, 2016). "Additionally, ITPA mutation has been shown to cause early infantile encephalopathy and variation has been linked to young-onset tuberculosis susceptibility." (PMID 27770805, 2016).
colorectal cancer (3 papers, 2016 to 2024). A primary or metastatic malignant neoplasm that affects the colon or rectum. "ITPA deficiency induces cell growth delay via upregulating P21 expression in human colorectal cancer." (PMID 36899424, 2023). "Western blot analysis showed that the level of ITPA in WI38 cells was essentially the same as in various other cell lines, including HeLa MR cells, another normal fibroblast cell, IMR90, and cell lines derived from human colorectal cancer (HCT116 and H414)." (PMID 27618981, 2016).
developmental delay (3 papers, 2019 to 2024). "ITPA polymorphism affects a substantial number of individuals and can affect clinical outcomes or result in severe developmental delays and infantile death." (PMID 38066288, 2024). "A 17-month-old child with a global developmental delay was diagnosed with an inosine triphosphate phosphohydrolase deficiency based on homozygous pathogenic variants in the ITPA gene, c.137delA (pGln46ArgfsTer43)." (PMID 36004034, 2022).
dilated cardiomyopathy (3 papers, 2019 to 2024). Cardiomyopathy which is characterized by dilation and contractile dysfunction of the left and right ventricles. "Genetic defects in the ITPA gene are closely related to human diseases including early infantile encephalopathy, infantile dilated cardiomyopathy, and neural depolarization and epilepsy." (PMID 39189649, 2024).
infantile epileptic encephalopathy (3 papers, 2019 to 2022). an epileptic condition characterized by epileptiform abnormalities associated with progressive cerebral dysfunction. "However, the incorporation of ITP/XTP, dITP/dXTP, or the genetic deficiency or polymorphism of the ITPA gene have been implicated in many human diseases, including infantile epileptic encephalopathy, early onset of tuberculosis, and the responsiveness of patients to cancer therapy." (PMID 35159194, 2022).
inflammatory bowel disease (3 papers, 2018 to 2022). A spectrum of small and large bowel inflammatory diseases of unknown etiology. "Nevertheless, a trial of about 550 adults with inflammatory bowel disease (IBD) showed that the ITPA allele has nothing to do with treatment-related ADR." (PMID 35935867, 2022). "In patients with inflammatory bowel disease using azathioprine, however, adverse events occurred more frequently in patients with ITPase lowering ITPA polymorphisms." (PMID 29329318, 2018).
microcephaly (3 papers, 2019 to 2022). A congenital or acquired developmental disorder in which the circumference of the head is smaller than normal for the person's age and sex. "Bi-allelic loss-of-function mutations were recently reported in ITPA in seven affected individuals from four families with early-infantile encephalopathy, a distinctive pattern of white matter disease evident on brain MR imaging, microcephaly and progressive neurological disease." (PMID 30856165, 2019).
myelosuppression (3 papers, 2015 to 2021). Myelosuppression or bone marrow suppression is a condition in which bone marrow activity is decreased, resulting in fewer red blood cells, white blood cells, and platelets. "In Japanese individuals, the ITPA gene polymorphism may be more influential compared with the TPMT polymorphism in inducing thiopurine-induced myelosuppression." (PMID 26360046, 2015). "Our findings suggest that the polymorphism of NUDT15 (415C>T) is a significantly relative factor in the context of AZA-induced myelosuppression, and epistatic interactions between ITPA (94C>A) and NUDT15 (415C>T) affect the occurrence of myelosuppression." (PMID 34084143, 2021).
tuberculosis (3 papers, 2016 to 2022). A chronic, recurrent infection caused by the bacterium Mycobacterium tuberculosis. "On the other hand, ITPA variation which is predicted to increase protein expression is thought to reduce susceptibility to tuberculosis." (PMID 27770805, 2016). "ITPA polymorphism has also been linked to early-onset tuberculosis susceptibility." (PMID 27770805, 2016). "Recently, the ITPA gene has been identified as a susceptibility gene for young-onset tuberculosis (TB)." (PMID 27770805, 2016). "By using next-generation sequencing techniques, ITPA polymorphism was identified in multiple juvenile patients from different families suffering from tuberculosis, with the expression of g.19176G > A and c.94C > A (p.Pro32Thr) related to juvenile TB patients." (PMID 35159194, 2022). "The human thymus tissue is found to express the highest amount of ITPA and the results found after the detailed study of ITPA expression in the thymus gland show that it may have a very strong role in the development and outbreak of tuberculosis." (PMID 35159194, 2022).
developmental and epileptic encephalopathy (2 papers, 2024 to 2026). An epilepsy associated with developmental impairment that may be due to either the underlying etiology or the superimposed epileptic activity, or both. "Within the cohort of patients experiencing developmental and epileptic encephalopathy (DEE), WES has revealed genetic variants in novel genes (FGF12, GABBR1, GABBR2, ITPA, KAT6A, PTPN23, RHOBTB2, SATB2) and candidate epilepsy-associated genes (CAMTA1, FAT3, GABRA6, HUWE1, PTCHD1)." (PMID 39523358, 2024).
haemolytic anaemia (2 papers, 2012 to 2022). "Studies have shown that G1 patients with inosine triphosphatase (ITPA) deficiency - a benign inherited enzymopathy in which inosine triphosphate accumulates in red blood cells, are protected from RBV-associated haemolytic anaemia." (PMID 22708649, 2012).
leukemia (2 papers, 2013 to 2023). A malignant (clonal) hematologic disorder, involving hematopoietic stem cells and characterized by the presence of primitive or atypical myeloid or lymphoid cells in the bone marrow and the blood. "For AML – one of the mixed-lineage leukemias – ITPA variants were at a lower frequency than normal." (PMID 23547827, 2013).
neurosyphilis (2 papers, 2015 to 2020). Infection of the brain or spinal cord by Treponema pallidum. "In contrast to this an ITPA index >2 correlates significantly with definite or probable neurosyphilis only in the subgroup of HIV-negatives (p = 0.025, odds ratio 8.2)." (PMID 26445822, 2015). "In HIV-negative patients with increased CSF cell counts and/or blood-CSF barrier damage and an increased ITpA or TPHA CSF/serum antibody index, treatment for neurosyphilis should be considered." (PMID 33225223, 2020).
rheumatoid arthritis (2 papers, 2015 to 2020). A chronic, systemic autoimmune disorder characterized by inflammation in the synovial membranes and articular surfaces. "Indeed, at least two proteins, ITPA and GPT2, are well-established therapeutic targets for rheumatoid arthritis and anxiety disorders with the FDA-approved inhibitors, azathioprine and phenelzine, respectively." (PMID 32873298, 2020).
uveal melanoma (2 papers, 2022). A melanoma derived from melanocytes of the uveal tract. "The experiment results illustrate that the ITPA gene may play a significant role in uveal melanoma cell survival." (PMID 35242144, 2022).
autoimmune hepatitis (1 paper, 2021). Hepatitis caused by autoantibodies. "This study aimed to investigate the influence of TPMT*3C, ITPA, NUDT15, and 6-thioguanine nucleotides (6-TGN) on azathioprine (AZA)-induced myelosuppression in Southwest China patients with autoimmune hepatitis (AIH)." (PMID 33846471, 2021).
breast carcinoma (1 paper, 2023). "Silencing of ITPA mediated by nano-carrier was reported to promote apoptosis in human breast cancer cells, which provides promise for targeted therapeutic application." (PMID 36899424, 2023).
cytomegalovirus pneumonia (1 paper, 2012). Pneumonia caused by cytomegalovirus. "A total of 5 patients relapsed in the ITPA variant group (BM = 1, CNS = 1, testis = 1, BM and CNS = 1, and BM and testis = 1), and 2 patients among them died due to transplantation-related complications (veno-occlusive disease, cytomegalovirus pneumonia)." (PMID 23029095, 2012).
developmental and epileptic encephalopathy, 35 (1 paper, 2022). "Developmental and epileptic encephalopathy 35 (DEE 35) is a severe neurological condition caused by biallelic variants in ITPA, encoding inosine triphosphate pyrophosphatase, an essential enzyme in purine metabolism." (PMID 34989426, 2022).
Hepatic fibrosis (1 paper, 2015). The presence of excessive fibrous connective tissue in the liver. "Among patients with advanced hepatic fibrosis, ITPA polymorphisms were associated with the severity of Hb decline at week 4, but not at week 12 of therapy." (PMID 26441325, 2015).
Hepatitis (1 paper, 2013). Inflammation of the liver. "For example, the SNP rs11697186 located in geneDDRGK1 near the ITPA gene (Inosine TriphosphatePyrophosphohydrolase) was significantly associated with response to hepatitis Ctreatment in a GWAS study, and later was found to be in high LD with SNP rs1127354 onITPA exon 2 by fine mapping." (PMID 23876401, 2013).
Infertility (1 paper, 2018). "While previous studies examined the role of the DNArepair system in gametogenesis, this paper analyzedthe association of rs7270101 SNP in the ITPA gene with thesusceptibility to infertility in the Iranian population." (PMID 29308621, 2018). "Weattempted to examine the association of two SNPs (rs1127354 and rs7270101) in ITPA, a gene encoding a key factorin the repair system, with susceptibility to infertility." (PMID 29308621, 2018). "It is well known that OS may affectsome key properties of sperm and ovum, however, noprevious study has examined the role of ITPA in infertility." (PMID 29308621, 2018).
liver diseases (1 paper, 2012). "For patients affected with HCV-related liver diseases, two important genetic polymorphisms, IL28B and ITPA, have been reported recently, which hopefully will lead to appropriate antiviral therapy for each individual." (PMID 23145809, 2012).
Sepsis (1 paper, 2012). Sepsis is defined as life-threatening organ dysfunction caused by a dysregulated host response to infection. "Because the incidence of febrile neutropenia or sepsis was not higher in ITPA variants and death did not occur during the courses of mercaptorpurine or methotrexate, the lower survival rate in the variant group might not be influenced by accumulated toxic metabolites, but by other factors." (PMID 23029095, 2012).